RNU6ATAC8P (RNA, U6atac small nuclear 8, pseudogene)
Gene: Small nuclear RNA gene on chromosome 8 (102,421,197 to 102,421,322, forward strand). Ensembl gene ENSG00000221387.
Homologues: Orthologues: chimpanzee RNU6ATAC8P (100% identical), macaque RNU6ATAC8P (94% identical). Paralogues in human: RNU6ATAC (87% identical), RNU6ATAC21P (85% identical), RNU6ATAC7P (81% identical), RNU6ATAC41P (80% identical), RNU6ATAC27P (79% identical), RNU6ATAC6P (78% identical), RNU6ATAC19P (60% identical), RNU6ATAC39P (53% identical), RNU6ATAC22P (52% identical).